HIF1A (hypoxia inducible factor 1 subunit alpha)
Diseases named in the same sentence as HIF1A in open-access papers (continued):
Sharing a sentence is not in itself a finding about the gene and the disease.
neurodegenerative disease (continued). "Once again, we have correlated treatment with DFO and modulation of the HIF‐1α and GSK‐3β pathways, which have been postulated to play an integral role in DFO's effects in animal models of brain injury and neurodegenerative disease." (PMID 31960628, 2020). "The increased expression of HIF1A suggests that FVSE may enhance resilience under metabolic stress, a common feature in neurodegenerative diseases." (PMID 39684414, 2024). "Here, microglial HIF-1α may be regarded as the core molecule of IIM, involved in regulating the pathological process of neurodegenerative diseases." (PMID 38555419, 2024). "In the context of neurodegenerative diseases, VHL interacts with DJ-1 and prevents HIF1α degradation by CUL2, which may partly explain the neuroprotective role of DJ-1 in Parkinson’s disease." (PMID 26751167, 2016).
inflammation (21 papers, 2014 to 2026). Aberrant reaction of the microcirculation characterized by movement of fluid and leukocytes from the blood into extravascular tissues. "Coumarin compound, emodin, alleviated LPS-induced pulmonary inflammation in rat lung tissues through inhibiting the mammalian target of rapamycin (mTOR)/hypoxia-inducible factor 1-alpha (HIF-1α)/vascular endothelial growth factor (VEGF) signaling pathway." (PMID 35002723, 2021). "We also generated Hif2af/f, Cd4CreHif2af/f and Cd4CreHif1af/fHif2af/f iTreg cells, and investigated if additional deletion of HIF-1α corrected the defects of HIF-2α-KO iTreg cells to suppress allergen-induced airway inflammation." (PMID 33024109, 2020). "Similar results were observed with this inhibitor, confirming the implication of HIF-1α in early lung inflammation induced by LCO." (PMID 31533843, 2019). "Taken together, our data demonstrate that VASP, which is negatively regulated by TNF-α, induces HIF-1α activation during the acute pulmonary inflammation process and plays an important role in the impairment of the alveolar-capillary barrier." (PMID 25051011, 2014). "Importantly, pharmacological targeting of HIF-1α pathways reduces METs formation, attenuates lung inflammation, and improves survival outcomes." (PMID 42193470, 2026). "In future studies, the expression of NFκB and HIF1α pathways should be scrutinized to understand whether dietary intervention can prevent PM-induced pulmonary inflammation and/or hypoxic events." (PMID 36901532, 2023). "The close relationship between HIF-1α and renal interstitial inflammation may be related to the release of inflammatory cytokines from renal tubular cells or the cross talk between renal tubular cells and macrophages." (PMID 34211565, 2021). "Additionally, HIF-1α inhibition reduced Th2 cytokines expression in CD8+ T cells upon hypoxia exposure, and the adoptive transfer of HIF-1α deficient CD8+ T cells underwent hypoxia attenuates AHR and airway inflammation in mice." (PMID 33519814, 2020). "Taken together, our data demonstrate that HIF-1α acts downstream of TNF-α to inhibit VASP expression and to modulate the acute pulmonary inflammation process, and these molecules play an important role in the impairment of the alveolar-capillary barrier." (PMID 25051011, 2014). "The finding of a novel functional HIF-1α-NF-κB-NLRP3 axis provides insight into the link between the hypoxic microenvironment and pulpal inflammation, thus supporting a promising therapeutic strategy for the control of pulpal inflammation." (PMID 39343901, 2024). "To test the implication of HIF-1α in LCO lung inflammation, we first used chetomin which binds to the Zn2+-binding cysteine/histidine rich 1 (CH1) domain of p300, leading to a reduction of the interaction between HIF-1α and P300 and reduces the expression of HIF-1α target genes." (PMID 31533843, 2019).
heart disease (18 papers, 2012 to 2025). "Conversely, HIF-1α functions as a key transcriptional regulator of hypoxic metabolic reprogramming and directly influences the expression of inflammatory factors, processes that are intricately associated with the complex pathogenesis of heart disease." (PMID 40944191, 2025). "We found that HIF-1α increased in all groups with heart disease, with an important increase during CR progression, especially in the HF phase." (PMID 37047174, 2023). "Analysis of evolution in animals with heart disease showed that HIF-1α was higher in AoSHF than AoS2 and AoS18." (PMID 37047174, 2023). "In cardiac disease, HIF-1α plays a key role in the regulation of multiple genes involved in the maintenance of oxygen homeostasis at a low oxygen level, regulating cell survival and differentiation." (PMID 38680230, 2022). "Long-standing evidence suggests that one isotype of HIF, HIF-1α, is involved in the pathogenesis of various solid tumors and cardiac diseases." (PMID 28289375, 2017). "Here, we report that transcription factor zinc finger E-box-binding homeobox 2 (ZEB2) is induced by hypoxia-inducible factor 1-alpha (HIF1α) in hypoxic cardiomyocytes and regulates a network of genes involved in Ca2+ handling and contractility during ischaemic heart disease." (PMID 39308239, 2024). "Thus, the activation of KHK and HIF-1α are likely critical factors contributing to mediating heart disease in this condition." (PMID 37237888, 2023). "The present study revealed that HIF‐1α played an important role during ET‐induced myocardial angiogenesis and cardiac function in MI rats, thus providing new insights on the rehabilitation mechanism of ischaemic heart diseases." (PMID 32939968, 2020). "Hence, GPER may be considered as a further therapeutic target in cardiac diseases on the basis of its involvement in myocardial inotropism and lusitropism as well as in the expression of the apoptotic and fibrotic factors HIF-1α and CTGF, respectively." (PMID 23950890, 2013). "Our study demonstrates a pathological role for amylin in the activation of HIF1α and PFKFB3 signaling in NHPs with HF, establishing amylin as a promising target for heart disease patients." (PMID 33580152, 2021). "Some of those genes, including ITGA4, ITGB8, MYL7, ITGB7, HIF-1α and BNP, are assosiated with heart disease pathways and are recognized as myocardial injury biomarkers." (PMID 28692647, 2017). "In our series, RA HIF-1α-mRNA was not differentially expressed in the different patient groups related to their principal cardiac disease." (PMID 39708201, 2024).
neurological disorders (14 papers, 2009 to 2025). "A Mendelian randomized study was used to investigate the existence of a causal relationship between plasma HIF‐1α and neurological diseases." (PMID 40022282, 2025). "This MR study provided population‐based proof for the genetic associations between HIF‐1α levels and neurological diseases." (PMID 40022282, 2025). "Heterogeneity and pleiotropy tests for the associations of plasma HIF‐1α levels with neurological diseases." (PMID 40022282, 2025). "Using a two‐sample MR method, we provide a thorough investigation to determine the causal relationships between plasma HIF‐1α levels and various neurological disorders." (PMID 40022282, 2025). "Recent studies revealed that tubulin isotypes caused a variety of neurological disorders and tubulin-binding drugs can activate a component of the hypoxic adaptive response, specifically the stabilization of HIF-1α and its downstream targets." (PMID 33008433, 2020). "Sensitivity analysis of the associations between plasma HIF‐1α levels and neurological diseases." (PMID 40022282, 2025). "However, whether a causal relationship exists between plasma HIF‐1α levels and neurological diseases remains unclear." (PMID 40022282, 2025). "HBOT is evidenced to suppress the HIF-1α expression by the increase of oxygen context in CNS lesions of neurological disorders and to promote the angiogenesis via the production of VEGF." (PMID 34440146, 2021). "The role of HIF-1α in neurological disorders remains controversial." (PMID 40653468, 2025). "We wonder whether Hif1α and Hif2α are also elevated in vivo and play a similar role in neurological disorder of Irp2–/– mice." (PMID 34675764, 2021). "For example, prolyl hydroxylase domain enzymes (PHD), the classical Hypoxia Inducible Factor-1alpha (HIF-1α) hydroxylation-modifying enzymes under normoxia, have been identified as the critical targets of iron chelators that are clinically beneficial in many neurological disorders." (PMID 34199597, 2021). "This study provides a concrete platform to further investigate the modulation and interaction of Hif-1α and JNK signaling pathways with the goal of providing novel therapeutical targets to treat hypoxia-related neurological disorders." (PMID 20110876, 2009). "HIF-1α also upregulates a plethora of genes including vascular endothelial growth factor (VEGF) and erythropoietin, both showing neuroprotective activity in different animal models of neurological diseases." (PMID 34339019, 2021).
hematological malignancies (13 papers, 2015 to 2026). "Conversely, although hypoxia is a physiological hallmark of hematopoietic organs, the contribution of HIF1α and HIF2α to hematological malignancies has been underestimated for a long time." (PMID 36059690, 2022). "Among them, hypoxia-inducible factor 1-alpha (HIF-1α) is a central regulator of hypoxic responses and hematopoiesis, supporting stem cell maintenance and erythropoiesis, while playing complex roles in hematologic malignancies." (PMID 41562686, 2026). "In this review, we briefly outline the basic structure and biological functions of HIF-1α and discuss the progress of research on HIF-1α in multiple solid tumors and hematological malignancies." (PMID 37588219, 2024). "Transcription factors activated in both liver and muscle include Irf8, Jun, Egr1, Cebpa, Foxl2, the hypoxia-inducible factor Hif1a, and Runx1, a key regulator in hematological malignancies." (PMID 35865523, 2022). "This suggests that HIF‐1α is correlated with poor prognosis; the increased level of lactate dehydrogenase negatively affects the medical outcomes of hematologic malignancies." (PMID 31411003, 2019). "The HIF1α-Notch pathway is proposed to be essential for maintenance of CSCs in hematological malignancies under conditions of normoxia." (PMID 25749383, 2015). "Previous research has shown that AHR and HIF-1α are important in hematological malignancies." (PMID 34572746, 2021). "Knockdown or inhibition of HIF-1α abrogates CSCs in hematological malignancies." (PMID 30630537, 2019). "Phenotypically, mutant ASXL1 impairs the BAP1-ASXL1-FOXK1/K2 transcriptional nexus and downregulates TXNIP, VHL, and SOCS1/2, and consequently promotes glucose metabolism and enhances oncogenic HIF-1α and JAK-STAT3 signaling pathways known to be altered in hematological malignancies." (PMID 32683582, 2021). "In hematologic malignancies the mTOR activation, working in opposition with AMPK but in concert with other oncogenes such as Bcr-Abl, or metabolic modulators like HIF1α, contributes to confer the glycolytic phenotype by directly and indirectly regulating key glycolytic enzyme activity." (PMID 32053876, 2020).
benign tumors (11 papers, 2005 to 2022). "HIF-1α is positively expressed in 87.8% (36/41) epithelial cancer, 90% (18/20) borderline cancer, 40.7% (11/27) benign tumors and 17.9% (5/28) normal tissues." (PMID 23545606, 2013). "Therapy based on expression of HIF-1α can be regarded as a strategy to induce neoangiogenesis in the ischemic heart." (PMID 24069057, 2013). "However, for benign neoplasms, especially intracranial benign tumors, little attention has been paid to HIF-1α." (PMID 36091021, 2022). "Therefore, in this study, we investigated whether there is any difference in the expression of HIF-1α and HIF-2α between malignant and benign neoplasms, as well as non-neoplastic thyroid lesions." (PMID 29084538, 2017).
infectious disease (9 papers, 2012 to 2026). A disorder directly resulting from the presence and activity of a microbial, viral, or parasitic agent in humans. "For fish, few studies show a clear relationship among HIF-1α, oxidative stress, and infectious diseases." (PMID 34785749, 2021). "The role of HIF-1α in other ailments and infectious diseases (e.g. bacterial) has been extensively reviewed by Semenza and dos Santos." (PMID 33135539, 2020). "Thus, HIF-1α may be a potential therapeutic target for treatment of HTLV-1 infectious diseases." (PMID 25522269, 2014). "It is currently unknown however, whether the interactions of HIF-1α and NF-κB pathways also affect the EPO-EPOR system in infectious diseases." (PMID 22094132, 2012).
immune dysfunction (8 papers, 2021 to 2025). "Mechanistically, the production by Vhl-deficient Treg cells of a large amount of Ifn-γ due to transactivation by accumulated Hif1α is responsible for immune-disorder phenotype, which was completely rescued by simultaneous Ifn-γ deficiency in Treg cells." (PMID 35641500, 2022). "Moreover, CAIX correlated with HIF-1α, PD-L1, and immunosuppressant molecules, linking hypoxia-driven metabolic alterations with immune dysfunction." (PMID 41226466, 2025). "We demonstrate that hypoxia-induced factor 1α (HIF1α) interaction with HDAC1 and concurrent PRC2 dependency causes chromatin remolding resulting in epigenetic suppression of effector genes and subsequent immune dysfunction." (PMID 35840558, 2022). "HIF-1α is related to immune system disease and displayed an obvious RNA expression difference." (PMID 34421593, 2021). "To explore the mechanisms of hypoxia-mediated immune dysfunction, we found that both persistent and intermittent hypoxia can directly trigger the overexpression of PD-L1 in various cell types and that these effects are closely related to HIF-1α activity." (PMID 34256773, 2021).
vasculopathy (8 papers, 2012 to 2025). "Impaired tissue repair and angiogenesis, involving FGF1, FGF2, TGF-β, VEGF, and HIF-1α, has been implicated in vasculopathy and pseudoaneurysm formation in STAT3-HIES." (PMID 40491905, 2025). "HIF-1α is thought to have a protective effect in vascular disorders as it induces mature vessel formation." (PMID 38333571, 2024). "High expression of HIF-1α within endothelial plexiform lesions and ASMC suggests a strong correlation between HIF-1α and proliferative vasculopathy." (PMID 28611671, 2017). "Furthermore, in silico analyses indicated interactions of miR-199a-5p with HIF1A, Ets-1, and TGFB2 genes, which are associated with vasculopathy and reduced NO." (PMID 35204817, 2022). "Indeed, circulating monocytes and monocyte-derived macrophages from patients with fibroinflammatory vasculopathy are highly efficient in glucose import and are expressing higher glycolysis-associated genes (GLUT1, HK2, PKM2, LDH, c-myc, and HIF-1α) in comparison to healthy individuals." (PMID 37415975, 2023).
head and neck tumors (7 papers, 2009 to 2025). "Our study is the first to demonstrate that ibuprofen downregulates carbonic anhydrase IX expression in hypoxic colon and head and neck tumor cells by decreasing HIF-1α levels." (PMID 40408503, 2025). "Less controversy surrounds the expression of HIF-1α, the endogenous regulator of glucose metabolism mechanisms in hypoxia conditions, with regard to clinicopathological parameters in various types of head and neck neoplasms." (PMID 25412955, 2015). "Furthermore, head and neck tumors with high HIF-1α expression tend to be more sensitive to RT due to the facilitated generation of reactive oxygen species in a more vascularized microenvironment." (PMID 39684225, 2024). "The results in RC2 cells expressing HIF-1α are consistent with our previous findings of HIF-1α inhibition by MSA resulted in the downregulation of VEGF and growth inhibition in head & neck tumors." (PMID 22804960, 2012). "Previous studies have also reported a lower prevalence or absence of HIF-1α in noncancerous tissue of various head and neck tumors." (PMID 25412955, 2015). "In support of this hypothesis a recent clinical study has revealed a negative correlation between pre-treatment HIF-1α expression in head and neck tumors and overall survival after concomitant cisplatin-based radiochemotherapy." (PMID 25234922, 2014).
liver (7 papers, 2008 to 2025). "The HIF-1α/MMPs and HIF-1α/ADAMs signaling pathways play a vital role in the immune escape of digestive system tumors." (PMID 40563539, 2025). "In summary, the HIF-1α/MMPs signaling pathway and the HIF-1α/ADAMs signaling pathway are generally abnormally activated in digestive system tumors." (PMID 40563539, 2025). "Hence, the HIF-1α/MMPs or HIF-1α/ADAMs signaling pathways can be regarded as the key elements for immune escape against NK cells in digestive system tumors." (PMID 40563539, 2025). "The expression of HIF-1α in digestive system tumors was analyzed using GEPIA 2.0 software." (PMID 40563539, 2025). "We reviewed the HIF-1α/MMP or HIF-1α/ADAM signaling pathways and immune escape mechanisms in common digestive system tumors." (PMID 40563539, 2025).
brain diseases (6 papers, 2017 to 2024). "This review has revealed the molecular mechanisms of a key molecule, HIF-1α, during severe hypoxic conditions, such as those in brain diseases." (PMID 38674050, 2024). "Developing techniques to diminish HIF-1α during severe hypoxia is valuable, creating a new direction for brain disease treatment." (PMID 38674050, 2024). "Deciphering the molecular mechanisms of HIF-1α will contribute to the development of therapeutic strategies for severe hypoxic brain diseases." (PMID 38674050, 2024). "Further investigation of HIF‐1α is warranted to assess the beneficial aspects of microglial metabolic regulation by HIF‐1α in brain disorders." (PMID 35751629, 2022). "Although HIF-1α and VEGF have been widely known to be elevated in brain diseases, but the exact roles of HIF-1α and VEGF in ACI combined with CCS are still being unsolved." (PMID 37600117, 2023).
intestinal disease (6 papers, 2013 to 2025). "It is also highlighted that HIF-1α has the potential to treat intestinal disorders by targeting signaling pathways associated with hypoxia." (PMID 36768744, 2023). "Previous studies have found that physiological HIF-1α expression provides a barrier-protective function in intestinal disease." (PMID 37507801, 2023). "Our data suggest that pharmacologic modulation of the SUMO pathway with TAK-981 positively regulates HIF-1α in our system, thereby highlighting the potential benefit of using TAK-981 to enhance activity of hydroxylase inhibitors in the treatment of intestinal disorders." (PMID 37742924, 2023).
respiratory diseases (6 papers, 2016 to 2024). "Furthermoree, knowing that SNPs within the HIF1A gene are associated with respiratory diseases future studies can now refine our understanding of the associated phenotypes by looking at differences between patients with and without these SNPs." (PMID 34621299, 2021). "Based on current findings, the diagnostic roles of HIF‐1α mRNA for patients with other respiratory diseases (eg, COPD) + OSAHS could also be investigated in future works." (PMID 32896931, 2020). "Hypoxia-induced ROS accumulation and activated HIF-1α lead to attenuated osteogenesis and enhanced osteoclastogenesis in patients with respiratory diseases." (PMID 35903070, 2022). "Moreover, inflammatory and reparative activities of lung macrophages are regulated by β-catenin-HIF-1α signaling, with implications for the treatment of severe respiratory diseases including COVID-1919." (PMID 37291167, 2023).